TNF (tumor necrosis factor)
Diseases named in the same sentence as TNF in open-access papers (continued):
Sharing a sentence is not in itself a finding about the gene and the disease.
tumor (continued). "Compared to naïve mBMDNs, HCC exosome-reprogrammed mBMDNs significantly promoted the formation of tumor nodules, increased the expression of PD-1 and Tim3, and reduced the expression of IFN-γ and TNF-α in liver-infiltrating CD8+ T cells and CD4+ T cells." (PMID 40083930, 2025). "Moreover, CD4+ T cells may also exert antitumor effects by assisting CD8+ T cells or, in some cases, directly recognizing antigens presented on the surface of tumor cells eventually followed by secretion of type 1 cytokines (TNF-α or IFN-γ) or direct cancer killing." (PMID 41029711, 2025). "Second, in the tumor microenvironment, TILs secrete cytokines (IFN‐γ, TNF‐α) to modulate immune responses and have an impact on angiogenesis." (PMID 40673386, 2025). "Emerging evidence suggests that activating neutrophils has therapeutic effects in tumor immunotherapy, including the Bacillus Calmette-Guérin (BCG), β-glucan, or a combination therapy involving anti-CD40 antibodies, TNF-α, and tumor-binding antibodies." (PMID 39925807, 2025). "In particular, it suppressed Ki67+CD8+, TNFα+CD8+, and IFNγ+CD8+ T cells while restoring PD‐1+CD8+ and TIM‐3+CD8+ T cells in tumor lesions." (PMID 39903759, 2025). "TNF-α also has a dual role in the TME, as it can either promote anti-tumor immune responses or contribute to tumor progression depending on the context." (PMID 40486614, 2025). "In cachexia-prone malignancies, the TME is enriched with pro-inflammatory cytokines such as IL-6, TNF-α, IL-1β, and IFN-γ, secreted by both tumor and immune cells including macrophages, MDSCs, and T cells." (PMID 40704145, 2025). "To further characterize the impact of IFN-γ and TNF-α on tumor growth, we neutralized IFN-γ and TNF-α in mice bearing either LLCova or B16ova tumors." (PMID 40553564, 2025). "The expression profiles of IL1β, IL10, IL18, TNF-α, TLR4, GATA3, and CD68 in HHV-infected PCa FFPE biopsies indicated an inflammatory environment conducive to immune alteration and potential tumour progression." (PMID 40430084, 2025). "After this repolarization of TAMs in the tumor microenvironment, M1 macrophages would directly kill tumor cells by secreting interferon gamma (IFN-γ) and tumor necrosis factor alpha (TNF-α) etc." (PMID 39839492, 2025). "This is further supported by our data showing that coculturing PSCA CAR_sIL-15 iNKT cells with either gemcitabine-sensitive or GR PSCA+ tumor cells boosts secretion of granzyme B, IFN-γ, and TNF-α when compared with control sIL-15 iNKT cells." (PMID 40231459, 2025). "Tetramer-positive iNKT cells correlated negatively with tumor volume at endpoint and demonstrated increased intracellular IFN-γ and TNF-α, indicating an improved antitumor immune response after BCAA supplementation." (PMID 40272913, 2025). "Cytokine expression analysis revealed upregulation of IL-1α, IL-2, IL-4, and TNFα and downregulation of IL-6 and IL-8 in JX14P TAMs compared to JX14P-RT TAMs, suggesting that JX14P-RT TAMs have a higher capacity for tumor-promoting inflammation." (PMID 40386422, 2025). "Consistent with the slower tumor growth in the triple therapy + LC cohort, we measured increased cytotoxic CD4+GrB+, CD4+, and CD8+ IFNγ+TNFα+ and a trend to more memory T cells and fewer CD8+ regulatory T cells (Tregs) in the tumors." (PMID 41171165, 2025). "Once activated, CD8+ T cells recognize tumor cells presenting the same antigens and induce cytotoxic effects through the release of IFN-γ, TNF-α, TRAIL, and FasL, leading to apoptosis and tumor cell lysis." (PMID 40754671, 2025). "Increased IL6 and TNFα expression in this study suggests that TGM7 silencing disrupts inflammatory regulation, creating a tumor-supportive microenvironment." (PMID 41425727, 2025). "The combined effects of IL-10, TNF-α, and IFN-γ further induce B7-H4 on tumor cells, thereby promoting T-cell apoptosis and impeding cytotoxic lymphocyte-mediated tumor eradication." (PMID 41058699, 2025).
tumor (continued). "Six overlapping hub genes (CD8A, CDC20, E2F1, IL10, TNF, VCAM1) were overexpressed in GS 10 tumors, reflecting key pathways in tumor progression." (PMID 40227503, 2025). "The elevated expression of several cytokines such as IL-1β, IL-6, IL-10, TNF-α, and TGF-β has been reported to be involved in tumor initiation and progression in various types of cancer." (PMID 40722593, 2025). "Consistently, the combination regimen substantially elevated the concentrations of TNF-α, IFN-γ, and IL-2 in peripheral blood, spleen, and tumor tissue." (PMID 41408296, 2025). "As a tumor suppressor, WWOX acts as a downstream effector of the tumor necrosis factor (TNF) signaling pathway." (PMID 40006511, 2025). "These pathways are of particular interest in the field of cell therapy, as cytotoxic T cells primarily release TNF-α and IFN-γ to induce tumor cell apoptosis and increase tumor cell sensitivity to perforin/granzyme- and Fas/FasL-mediated cell death." (PMID 39965008, 2025). "The intervention with TNF-α resulted in a significant reduction of CD3+, CD4+, and CD8+ T cell infiltration in the tumor microenvironment, alongside alterations in the tumor compartments." (PMID 40861469, 2025). "In early tumor stages, IFN-γ, TNF-α, and lipopolysaccharide induce polarization of the M1 phenotype." (PMID 40297580, 2025). "Related to that, in glioblastoma, BCP was reported to work as a tumor suppressor, regulating the CB2 receptor that activates PPARg and inhibits NF-κB and TNF-a, and subsequently reduces Jun N-Terminal Kinase (JNK) expression." (PMID 40333803, 2025). "Chronic inflammation plays a crucial role, as pro-inflammatory mediators—such as S100A8/A9, tumor necrosis factor-α (TNF-α), and the TLR4-NF-κB signaling pathway—recruit myeloid cells and activate the endothelium, facilitating tumor extravasation." (PMID 40909970, 2025). "TNF-α and interferon-gamma (IFN-γ), released by immune cells, play complex roles in inflammation and tumor progression, affecting cell invasion and interactions with surrounding tissues." (PMID 40061139, 2025). "TNF-α and IL-6 are key inflammatory cytokines involved in immune suppression and tumorigenesis in CRC, providing growth and expansion signals to tumor progenitor cells and enhancing CRC development." (PMID 41200195, 2025). "Activated CD8+ T cells play a key role in anti-tumour immunity by transporting to the TME secreting factors such as perforin, TNF-α and FASL to exert cytotoxic effects performing effector functions to induce target cell death." (PMID 40495147, 2025). "The expression of CD86 and CD206 as well as M2/M1 index were detected by FCM to identify TAM phenotype, while cytokines related to macrophage activation, including IL-6, TNF-α, and CXCL10, were determined in tumor tissue and serum after treatment." (PMID 39744236, 2025). "Higher TNF-α/IL-33 and TNF-α/IL-4 ratios in responders suggest the predominance of proinflammatory potent stimulator TNF-α of anti-tumor immune response in NET patients who responded better to therapy and diminished immunosuppressive effect of IL-33 and IL-4." (PMID 40943444, 2025). "When the semi-quantitative IRS values were compared between tumour tissues and the corresponding margins, TNF-α, IFN-γ, IL-12 and IL-2 showed relatively lower expression in tumours, whereas IL-1β and IL-6 were elevated in tumour tissue." (PMID 41465261, 2025). "TNFα and IFNβ are also released upon activation of IFI16, which was elevated in the HPV16-related OPSCC tumor model compared to other models." (PMID 41401057, 2025). "DAMPs in ferroptotic tumor cells bind to advanced glycosylation end-product specific receptors (AGER), stimulating the production of tumor necrosis factor (TNF)." (PMID 40285867, 2025). "Our findings indicated that the knockdown of PRMT5 in the tumor microenvironment resulted in increased levels of IFN-γ and TNF-α expression in both CD4+ and CD8+ T cells." (PMID 41463372, 2025).
tumor (continued). "By producing cytokines, such as interferon, TNF, IL-10, IL-12, and VEGF, controlling the PD-1/PD-L1 signaling axis, and suppressing anti-tumor immune responses, M2 TAMs attract immunosuppressive cells and cause the depletion of cytotoxic T cells." (PMID 40426851, 2025). "On one hand, eosinophils directly attack tumor cells via eosinophil peroxidase (EPX) or eosinophil-derived neurotoxin (EDN), or indirectly stimulate macrophages to release TNF-α and H2O2." (PMID 40380196, 2025). "Meanwhile, anti-cytokine therapies, such as infliximab, which blocks tumor necrosis factor (TNF), or siltuximab, which targets IL-6, intervene in tumor progression by inhibiting pro-tumorigenic cytokines." (PMID 40136462, 2025). "Both cytotoxic subsets secrete substantial amounts of the anti-tumor cytokines interferon-gamma (IFN-γ) and tumor necrosis factor-alpha (TNFα), contributing to their tumor-suppressive functions." (PMID 40361239, 2025). "Recently, the pro-metastatic function of TNF-α and its involvement in the EMT for tumor cell migration to initiate metastasis were reported." (PMID 40933989, 2025). "Th1 cytokines like IFN-γ and TNF-α enhance the cytotoxicity of CD8+ T cells, activate M1-type TAMs, and promote their ability to phagocytose and kill tumor cells." (PMID 40255905, 2025). "This led to enhanced NK cell activation and increased secretion of tumor necrosis factor-α (TNF-α) and IFN-γ, ultimately suppressing tumor growth in both xenograft and orthotopic models." (PMID 41376820, 2025). "TNFα blockade stimulates vascular endothelial growth factor (VEGF) expression, facilitating angiogenesis and tumor growth." (PMID 40282506, 2025). "Furthermore, the relationship between M1-like macrophages and tumor metastasis may be partially attributed to the influence of inflammatory cytokines, such as IL-1β, TNF-α, and IL-6, which can directly or indirectly promote the proliferation of endothelial cells." (PMID 40438141, 2025). "NPC2 positive macrophages secrete TNF and TGFB1 that act on tumor cells, thereby enhancing the proliferation of tumor cells." (PMID 40620715, 2025). "Interestingly we will find that TNFα tends to associate with N1-type TANs, which may suggest a novel immunoregulatory network between TNFα, N1-type TANs and B-cells, in which the interaction between TANs and B-cells is critical for the formation of tumor immune response." (PMID 40160822, 2025). "NK cells’ supernatants or IFN-γ and TNF-α-induced tumor differentiation was blocked when we used antibodies against IFN-γ and TNF-α." (PMID 39851518, 2025). "In conjunction with replication, the virus produces interleukin-2 (IL-2) and tumor necrosis factor (TNF), which results in the recruitment of immune cells to the tumor microenvironment (TME)." (PMID 40107242, 2025). "Tumor samples exhibited significantly elevated expression of multiple immune- and inflammation-related genes, including MMP9, TNF, and members of the S100A family." (PMID 40678068, 2025). "Elevated TNF and IFN-γ, primarily secreted by activated CD8+ T cells, indicate enhanced specific immune-mediated tumor killing." (PMID 40698084, 2025). "The combination therapy not only reduced angiogenesis but also suppressed tumor progression and EMT, highlighting the therapeutic potential of targeting TNF-α in refractory TNBC." (PMID 40868199, 2025). "Within the tumor cell-specific data, GSEA showed a strong enrichment of TNF-α signaling pathways, confirming that tumor cells reacted to the exogenous treatment." (PMID 39762215, 2025). "CAFs are activated by inflammatory mediators within the TME, encompassing soluble factors generated by the tumor, such as transforming growth factor beta (TGF-β), interleukin-1 (IL-1), interleukin-6 (IL-6), and tumor necrosis factor-alpha (TNF-α)." (PMID 39935427, 2025).
tumor (continued). "As a consequence of this immune activation, the tumor microenvironment becomes enriched with pro-inflammatory cytokines, such as interleukin-2 (IL-2), interleukin-6 (IL-6), interferon gamma (IFN-γ), and tumor necrosis factor alpha (TNF-α)." (PMID 40807154, 2025). "There was a notable augmentation in tumor-infiltrating CD45+ lymphocytes and mature DCs, an escalation in the proportion of CTLs, and a heightened secretion of IFN-γ and TNF-α." (PMID 40698137, 2025). "Combined production of TNF-α and IFN-γ from CD4 T cells has been shown to alter the tumor microenvironment sensitizing tumors to various types of chemotherapy, such as treatment with cyclophosphamide and 5-fluorouracil." (PMID 40429884, 2025). "Preclinical studies with TNF-α inhibitors, including infliximab and antibodies targeting transmembrane TNF-α, have demonstrated reduced tumor growth, metastasis, and synergistic effects with chemotherapy in BC models." (PMID 40868199, 2025). "Immune modulation: Tumour-derived EVs containing miR-21 and miR-29a bind Toll-like receptors (TLR7/8) on immune cells, triggering an NF-κB–mediated inflammatory cascade (↑TNFα, IL-6) that promotes tumour growth and metastasis." (PMID 41311647, 2025). "Inflammatory mediators—such as TNF‐α, IL‐1β, iNOS, and COX2—act as molecular accelerants of tumor initiation and progression by fostering genomic instability, promoting cellular proliferation, and suppressing tumor immune surveillance." (PMID 41200213, 2025). "Myeloid DCs (mDCs), stimulated by tumor necrosis factor alpha (TNF-α), activate T cells, inducing tumor cell apoptosis, contributing to the support of an antitumor response." (PMID 41228278, 2025). "The inflammatory factor tumor necrosis factor-alpha(TNF-α), secreted by macrophages, can activate cJUN/Activator protein 1(AP1), leading tumor cells to transition from the CLA subtype to the BL subtype, which is associated with a poorer prognosis." (PMID 40861469, 2025). "Macrophages and OS cells emerged as dominant sources of multiple tumor-relevant signals, including SPP1, TNF, MIF, GALECTIN, ANNEXIN, and VEGF." (PMID 40895569, 2025). "Specifically, we found that CD8+ T cells promoted homing of CD4+Foxp3+ Tregs to the tumor bed by increasing the levels of CCR5 chemokines in the tumor microenvironment in an IFN-γ– and TNF-α–dependent manner." (PMID 40553564, 2025). "Our upcoming studies will also evaluate the interplay between TNFα, IFNγ, PGE2, and alternative NF-κB in regulating the balance between the pro- and anti-tumor functions of different myeloid cell types." (PMID 41142824, 2025). "Inflammatory stimuli such as IL-1B, IL-18, and TNF-a, along with activation of the NLRP3 inflammasome and chronic endoplasmic reticulum (ER) stress, promote hepatocyte damage and tumor progression." (PMID 41012682, 2025). "M1 macrophages produce proinflammatory cytokines such as TNF-α and IL-12, which support antitumour immunity, whereas M2 macrophages secrete immunosuppressive cytokines such as IL-10 and TGF-β, which promote tumour growth and immune tolerance." (PMID 41163221, 2025). "g., iNOS, COX-2, IL-1β, TNF-α), and thereby inhibits the MAPK pathway, exerting inflammation-suppressing and anti-tumor effects." (PMID 40766304, 2025). "NK cells exert their anti-tumor effects primarily by secreting perforin, granzyme B, and cytokines such as IFN-γ and TNF-α." (PMID 41280896, 2025). "M1 polarization, which promotes tumor suppression, is driven by IFN-γ, TNF-α, and TLR signaling through pathways like JAK/STAT1, NF-κB, and MAPKs (JNK, ERK), resulting in the production of pro-inflammatory cytokines and reactive oxygen species." (PMID 40330466, 2025). "This was accompanied by increased tumor infiltration CD8+ T cell, as well as elevated production of IFN-γ and TNF-α by CD8+ T cells." (PMID 39990209, 2025).
tumor (continued). "Proliferation of mesothelial cells by crocidolite asbestos, the phorbol ester tumor promoter, TPA (12-O-tetradecanoylphorbol-13-acetate), and TNFα (Tumor Necrosis Factor alpha) suggest multiple cell pathways leading to tumor promotion in MMs." (PMID 40438058, 2025). "The enhanced anti-tumor effect of ISCU-deficient macrophages appeared to be dependent on increased CD8+ T cell infiltration and their augmented anti-tumor activity (e.g. TNF-α, IFN-γ and Granzyme B secretions) within the tumor microenvironment." (PMID 40541964, 2025). "TNF-α exerts its antitumor effect by promoting apoptosis of tumor cells, polarizing TAMs to the M1 phenotype, and promoting EMT of tumor cells." (PMID 40165901, 2025). "Pro-inflammatory cytokines, such as IL-6, tumor necrosis factor-alpha (TNF-α), and CRP, serve not only as biomarkers of inflammation but also actively contribute to promoting a tumor-supportive microenvironment." (PMID 41008741, 2025). "Radiation therapy induces the production of death receptors in tumor cells, which act by binding to activated T lymphocytes, such as TNF-α and TRAIL, to induce the secretion of chemokines by different types of tumor cells." (PMID 40109871, 2025). "Gene expression analysis revealed higher levels of activation, cytotoxicity, and memory markers (e.g., CD69, PRF1, TNF, KLRB1, and NCR3) in iMRAS-activated CAR-iNKT cells, correlating with their enhanced tumor-killing potential." (PMID 40297706, 2025). "Recent studies have further found that during CAR T-cell therapy, certain solid tumors respond to tumor necrosis factor secreted by CAR T-cells, which in turn promotes tumor cells to secrete small sEVs carrying tumor antigens." (PMID 41226585, 2025). "As an important inflammatory medium, Tumor Necrosis Factor-alpha (TNF-α) serves as a crucial component in stimulating inflammatory cells, maintaining cellular homeostasis, and promoting tumor development." (PMID 40247422, 2025). "KEGG enrichment analysis revealed that the therapeutic effect of TMF on the HeLa tumor was involved in multi‐signaling pathways such as \MAPK, TNF, and PD‐L1 expression and the PD‐1 checkpoint pathway in cancer." (PMID 41179362, 2025). "This material efficiently delivers tumor antigens (e.g., carcinoembryonic antigen, CEA) to dendritic cells, stimulating inflammatory cytokines (TNF-α, IL-6) and enhancing antigen presentation." (PMID 40521198, 2025). "CAF subtypes can secrete soluble factors, such as interleukin-6 (IL-6), TNF-α, and granulocyte-colony stimulating factor (G-SCF), that modulate the immune response, leading to either anti-tumor or pro-tumor effects." (PMID 39979981, 2025). "Additionally, cytokine analysis of sorted splenic Mac1+Gr-1+ myeloid cells from tumor-bearing mice revealed that compared with WT controls, cystatin C deletion significantly increased the expression of proinflammatory cytokines, including TNF-α, IL-1β, and IL-12." (PMID 41233352, 2025). "For example, the SCFAs pentanoate and butyrate can modulate the anti-tumor immune response by enhancing the production of TNFα and IFNγ by cytotoxic CD8 T cells, thus enhancing their anti-tumor activity." (PMID 41368640, 2025). "Significant differences in expression were observed for TNF-α, TGF-β, IL-1α, IL-1β, and IL-12 between PeIN and early (I + II) and advanced-stage (III + IV) tumours (Kruskal–Wallis test, p < 0.05)." (PMID 41465261, 2025). "On the one hand, inflammatory cells secrete a variety of cytokines and chemokines, such as interleukin-6 (IL-6) and tumor necrosis factor-α (TNF-α), which promote tumor cell proliferation, angiogenesis, and ECM remodeling." (PMID 41142435, 2025).